TFF2 (trefoil factor 2)
Diseases named in the same sentence as TFF2 in open-access papers (continued):
Sharing a sentence is not in itself a finding about the gene and the disease.
breast carcinoma (13 papers, 2014 to 2025). "Therefore, the ROC curve for serum TFF2 is the diagnostic accuracy of lower serum TFF2 in breast cancer patients." (PMID 28687783, 2017). "Therefore, the diagnostic accuracy of serum TFF2 is for lower serum TFF2 in breast cancer patients." (PMID 28687783, 2017). "The TFF family in mammals includes breast cancer-associated pS2 peptide (pS2/TFF1), spasmolytic polypeptide (SP/TFF2), and intestinal trefoil factor (ITF)." (PMID 37009791, 2023). "At that time, high serum TFF1 and low TFF2 can be used for more refining of breast cancer patients for the imaging examination." (PMID 28687783, 2017). "Serum TFF1 and TFF3 were significantly higher and serum TFF2 was significantly lower in breast cancer patients." (PMID 28687783, 2017). "Serum TFF2 levels in breast cancer patients were significantly lower than in healthy individuals (TFF1: 1.48 ± 1.43 ng/ml, P = 0.0004, TFF2: 3.90 ± 1.90 ng/ml, P = 0.0003, TFF3: 6.96 ± 1.45 ng/ml, P = 0.0313)." (PMID 28687783, 2017). "Breast cancer groups bearing germline and somatic BRCA2 mutations as well as non-mutated patients were characterized by the upregulation of luminal subtype signatures such as ESR1, TFF1, TFF2." (PMID 33525353, 2021). "Trefoil factor (TFF) peptides are family of small regulatory proteins consisting of three members, TFF1 (pS2), originally identified as an estrogen-responsive gene in the MCF-7 human breast cancer cell line, Spasmolytic polypeptide, TFF2 (SP), and intestinal trefoil factor, TFF3 (ITF)." (PMID 30744593, 2019). "0.72, and the order of accuracy for breast cancer patient screening was TFF2, TFF3 and TFF1." (PMID 28687783, 2017). "Only TFF2 was lower in breast cancer patients compared to healthy individuals." (PMID 28687783, 2017). "The serum TFF2 level in breast cancer patients was significantly lower than in healthy individuals." (PMID 28687783, 2017). "Additionally, the tumor suppressor effect of TFF2 was also found in prostate and breast cancer." (PMID 32122390, 2020). "Within this group of selected genes, we found the family of trefoil factor secreted peptides TFF1, TFF2 and TFF3, which are known to characterize luminal breast cancers." (PMID 35216615, 2022). "In this report, AUC of combination of serum TFF1, TFF2, and TFF3 is 0.96 suggesting that combined testing for TFF1, TFF2, and TFF3 can provide a powerful tool for breast cancer screening." (PMID 28687783, 2017). "TFF1, TFF2, and TFF3 values were all statistically different between breast cancer patients and healthy individuals." (PMID 28687783, 2017). "Serum screening with TFF1, TFF2, and TFF3 for breast cancer can increase the screening receiving rate." (PMID 28687783, 2017). "Serum TFF1, TFF2, and TFF3 in 94 breast cancer patients and 84 healthy individuals were measured and compared." (PMID 28687783, 2017). "For evaluation of the serum TFF1, TFF2, and TFF3 for cancer screening, serum of 22 breast cancer patients before treatment were evaluated." (PMID 28687783, 2017). "Immunohistochemical staining (IHC) for TFF1, TFF2, and TFF3 was performed for breast cancer tissue and normal epithelial tissue surrounding breast cancer." (PMID 28687783, 2017). "And denying the tumor volume in analyzing correlation between TFF1, TFF2, and TFF3 expressions in breast cancer tissue and serum TFF1, TFF2, and TFF3 is also a limitation." (PMID 28687783, 2017). "In the past, TFF3 - and TFF1, but not TFF2 - mRNA was detected in breast tumors and estrogen-responsive breast cancer cell lines and TFF3 was ranked among genes down-regulated in MDA-MB-231 compared to MCF7 cells." (PMID 35216615, 2022). "Immunohistochemically, TFF1 expression was positive in 56.5% and TFF3 was positive in 73.9% of breast cancers, while TFF2 was negative in all tumors." (PMID 28687783, 2017). "Serum concentrations of TFF1 and TFF3 but not TFF2 are higher in women with breast cancer than in women without breast cancer." (PMID 28687783, 2017).
breast carcinoma (continued). "We have analyzed serum TFF1, TFF2, and TFF3 as screening biomarkers for breast cancer." (PMID 28687783, 2017). "TFF2 was negative in both breast cancer tissue and normal epithelial tissue surrounding breast cancer." (PMID 28687783, 2017). "In summary, this study has demonstrated that the serum TFF1, TFF2, and TFF3 could be effective markers for breast cancer screening." (PMID 28687783, 2017). "In this study, we have analyzed whether serum TFF1, TFF2, and TFF3 can be biomarkers of breast cancer." (PMID 28687783, 2017). "Expression microarray analysis, which demonstrated consistent regulation of TFF1 and TFF3 but not TFF2 in three oestrogen-responsive breast cancer cell lines, was validated by real-time RT-PCR." (PMID 25900183, 2015). "The reason for lower serum TFF2 level in breast cancer patients is not known." (PMID 28687783, 2017). "However, TFF2 was negative in all of the breast cancer tissues." (PMID 28687783, 2017). "However, there was no co-relation between TFF1, TFF2, and TFF3 expression and ER in breast cancer tissue in this patients’ series." (PMID 28687783, 2017).
colitis (10 papers, 2016 to 2025). Inflammation of the colon. "p < 0.05), such as Retnlb (Resistin-like beta) and Tff2 (Trefoil factor 2), which are involved in colitis development." (PMID 38918576, 2024). "A similar protective effect against DSS-induced colitis was also obtained with a TFF2-secreting Lactococcus lactis strain, which had a therapeutic effect even in chronic colitis in Il10KO mice." (PMID 34066339, 2021). "Next we evaluated bioactivity of the modified TFF2 peptide by using DSS-induced colitis and AOM/DSS-induced colon cancer models." (PMID 30042499, 2019). "We tested the bioactivity of fusion TFF2-CTP-Flag in an in vitro assay using CD11b+Gr1+ cells sorted from the spleen of Tff2-null mice with DSS-induced colitis." (PMID 30042499, 2019). "Wild-type mice that received CD2–Tff2 bone marrow suffered the mildest colitis, while recipients of Tff2-null bone marrow had slightly more severe disease (measured by weight loss, spleen size, colonic shortening and colonic IL-1β expression)." (PMID 26841680, 2016). "In this study, the authors use a mouse model of colitis to demonstrate that upon vagus stimulation splenic memory T cells release TFF2, which suppresses the expansion of myeloid cells and cancer progression." (PMID 26841680, 2016). "Theoretically, this could diminish protection of the colonic stem cells by the Tff2/Muc6 complex and could lead to increased susceptibility of Tff1KO mice to DSS-induced colitis, similarly to what has been reported for Tff2KO mice." (PMID 37628863, 2023). "This in vitro result might be in agreement with an in vivo study, where colonic IL-6 production was dramatically reduced in a murine DSS colitis model after topical pretreatment (intracolonic route) with TFF2." (PMID 34066339, 2021). "Moreover, TFF2 can inhibit inducible nitric oxide synthase (iNOS) in monocytes and inflammatory compartments and regulate monocyte NO-mediated inflammation in colitis." (PMID 29783653, 2018). "Human TFF2 could enhance the rate of colonic epithelial repair, and reduce local inflammation in a rat colitis model." (PMID 27877172, 2016). "Therefore, we first induced colitis in wild-type mice (as well in Tff2-null mice) using 2.5% DSS in the drinking water for 5 days, followed on day 12 by the administration of Ad-Tff2 or Ad-Tff2-CTP-Flag, with additional mice treated with Ad-Fc or Ad-Fc-Flag as controls." (PMID 30042499, 2019). "We have previously demonstrated in a model of DSS-induced colitis that, in contrast to CD2-Tff2 mice, Tff2-null counterparts develop massive splenomegaly by 19–21 days due to the expansion of splenic myeloid CD11b+Gr-1+ cells." (PMID 30042499, 2019). "The colonic epithelium was found to be a larger source of trefoil factor 2 (TFF2) than colon leukocytes, and TFF2 was protective in both acute and chronic models of DSS-induced colitis." (PMID 29922293, 2018). "Following chemically induced colitis model (2.5% dextran sodium sulfate (DSS) ad libitum for 5 days), we observed a marked increase in splenic Tff2 expression within 24–72 h that subsided over 19 days (14 days after stopping DSS)." (PMID 26841680, 2016). "Surprisingly, the protective effect of TFF2 from DSS-induced colitis seemed to originate from colonic epithelial cells and not from colonic leucocytes, as TFF2 is not synthesized in the latter." (PMID 34066339, 2021). "Here, we show that, similar to Ad-Tff2, administration of Ad-Tff2-CTP-Flag decreases tumor number in AOM/DSS- treated mice and suppresses the expansion of CD11b+Gr-1+ cells (MDSCs) in the DSS-induced colitis model." (PMID 30042499, 2019). "The importance of T cells as a source of TFF2, as opposed to epithelial gastric cells, was confirmed by bone marrow transplantation of CD2–Tff2, wild-type or Tff2-null donor bone marrow into wild-type mice (5–6 mice per group), followed by the DSS colitis protocol." (PMID 26841680, 2016).
colitis (continued). "Thus, TFF2 did not significantly contribute to the colonic mucosal barrier and the increased expansion of immature myeloid cells and slightly worsened colitis after DSS in TFF2-null mice was not due to direct colonic effects by TFF2." (PMID 26841680, 2016).
Obesity (10 papers, 2015 to 2022). Accumulation of substantial excess body fat. "As an example of a potential signal molecule, the trefoil factor 2 (Tff2) has been identified as a newly found HF-specific gene for which its deficiency in mice leads to a protection from HF diet-induced obesity." (PMID 32752100, 2020). "This could allow for instance to evaluate the “predisposition” to develop HFD-induced obesity based on the expression intensity of TFF2/Tff2 following HFD." (PMID 34680900, 2021). "This correlated with our previous hypothesis in which TFF2 would be a signal aiming to limit the food intake and obesity development since CXCR4 deficiency would prevent TFF2 from playing the related metabolic roles in limiting obesity and thus, explains the exacerbated obesity." (PMID 34944474, 2021). "This explains why during obesity (such as in HF diet-induced obesity in animal models), those TFF2-correcting mechanisms are less efficient due to the strong immune-mediated damage that overcomes the TFF2-counteracting ability." (PMID 33494143, 2021). "The ultimate goal is to develop a novel generation of treatments and therapeutic targets for obesity and metabolic disorders that would pharmacologically target TFF2 pathways to mimic the antiobesity effects of Tff2 KO." (PMID 34436477, 2021). "Within this context, there is a potential to develop new treatments for obesity and related diseases by characterizing the molecular mechanisms by which TFF2 controls energy balance and target the related pathways." (PMID 34436477, 2021). "This highlights the importance of exploring TFF2-related pathways in the context of obesity management towards potential therapies." (PMID 33494143, 2021). "Such important molecular implication in obesity pathogenesis fits well and explains the reported protection from HF diet-induced obesity seen in Tff2 KO mice." (PMID 34436477, 2021). "The next objectives are to identify the mechanisms by which TFF2 regulates feeding, EE, and energy excretion, as well as explore the roles of TFF2 in obesity and related diseases." (PMID 34436477, 2021). "Ultimately, we would conclude that TFF2, as a lipid anabolic factor and a lipid absorption facilitator, would contribute to obesity establishment." (PMID 34436477, 2021). "Future studies will allow the characterization of potential therapeutic targets which can be used for the treatment of obesity and related diseases by the administration of the pharmaceutical inhibitors of TFF2 pathway among other options." (PMID 34436477, 2021). "Such food intake signaling would be an indirect mechanism by which TFF2 promotes tissue repair as well as a pathway worth exploring for potential obesity management pharmacotherapies." (PMID 33494143, 2021). "Among the TFFs, TFF2 has been shown to play a role in obesity and metabolic disorders, mainly after its characterization as an HFD-induced gene and the work that explored its metabolic implications." (PMID 34944474, 2021). "In order to elucidate the implications of TFF2 in the context of obesity, and more specifically in the HF-diet obesity, Tff2 knock-out (KO) mice were challenged with HFD." (PMID 34680900, 2021). "Among the hundreds of genes that are modulated after HF or LF meal ingestion, we put a spotlight on the Tff2 and its pathway as a potential targetable pathway for obesity molecular therapies." (PMID 32752100, 2020). "Although TFF2 has a different distribution along the GI tract than TFF3, genetic ablation of TFF2 confers resistance to diet-induced obesity corroborating the role of TFF family peptides interact in metabolic regulation." (PMID 26083576, 2015). "Knockout of mouse trefoil factor 2 protects against obesity in response to a high-fat diet." (PMID 36358920, 2022). "In the obesity context, the interactions between TFF2 and gut microbiota could be involved in the mechanisms of HFD-induced obesity." (PMID 34680900, 2021).
Obesity (continued). "Importantly, Tff2 KO protected the mice from the HFD-induced obesity, which was explained by a metabolic phenotype toward an increased energy expenditure." (PMID 34944474, 2021). "In our recent review, we have detailed a hypothesis that aims to explain how HFD induces Tff2 overexpression and at the same time the KO of this same gene, Tff2, lead to the protection from the HF-diet-induced obesity via metabolic changes." (PMID 34680900, 2021). "Indeed, whereas Tff2 has been reported as a gene that is specifically induced by HF diets in mice, its knockout protected mice from HF diet-induced obesity through a metabolic phenotype that contributes to more energy expenditure and reduced energy storage." (PMID 33494143, 2021). "Moreover, a chronic HF diet is also associated with obesity, which also affects the immunity and might explain some of the impacts obesity has on regeneration impairment through diverse processes, including inflammation, which is important in the context of TFF2′s roles in tissues repair." (PMID 33494143, 2021). "Interestingly, recent studies have highlighted metabolic implications of TFF2 especially in the context of obesity and HFD." (PMID 34680900, 2021). "Importantly, the hypothetical mechanisms pointed highlight TFF2 as an important contributor to obesity development via increasing lipids intestinal absorption and anabolism." (PMID 34436477, 2021). "Thus, TFF2/Tff2 expression has been suggested as an indicator of the severity of the HFD-induced obesity with a variety of potential applications." (PMID 34944474, 2021). "Indeed, measuring TFF2/TFF2/Tff2 expression in biological samples following the ingestion of high-fat diet reflects the biological “responsiveness” to the lipids ingestion and would reflect the severity of obesity establishment afterwards." (PMID 34680900, 2021). "Consequently, it is important to investigate the various mechanisms of action of TFF2 on energy balance corresponding not only to new, but also multiple opportunities to eventually prevent and treat obesity, which remains to this day a major challenge to public health providers." (PMID 34436477, 2021). "We believe this work represents an addition to our understanding of the lipidic molecular implications in obesity, which will contribute to develop therapies aiming to manage the lipidic metabolic pathways including the absorption, storage and metabolism via targeting TFF2-related pathways." (PMID 34436477, 2021). "In the context of obesity and high fat diet (HFD), Tff2 has been characterized as a HFD-induced gene." (PMID 34680900, 2021). "Based on such properties of Tff2 induction by HDF and its implications in HFD-induced obesity, potential applications can derive from and range from biomedical research to clinical practice." (PMID 34680900, 2021). "Since, we found no work focusing on TFF2 implications within either obesity or HF diet, it was important to focus our next exploration on the mechanisms of TFF2 involvement in energy balance from in vitro to in vivo." (PMID 34436477, 2021). "The knock-out of Tff2 in mice lead to the protection from HFD-induced obesity with a metabolic profile towards a negative energy balance." (PMID 34680900, 2021). "In boys, the prevalence of overweight and obesity combined increased to 28% at TFF2 (data not shown)." (PMID 31667452, 2019). "Therefore, TFF2 would represent a molecular mechanistic link between HFD and obesity development." (PMID 34680900, 2021). "We only found five genes shared between both groups (MUCL3, PGC, TCN1, TFF2, BPIFB1) that were upregulated in MO-low-IR but downregulated in MO-high-IR when compared with women without obesity." (PMID 35625760, 2022).
pancreatic cancer (8 papers, 2015 to 2025). "To evaluate the specificity of TFF2 as a diagnostic marker for pancreatic cancer, we examined its expression levels across publicly available datasets from the GEO database." (PMID 41040532, 2025). "Admittedly, the loss of TFF2 resulted in the development of pancreatic neoplasms." (PMID 38872370, 2024). "To determine the cell types responsible for TFF2 secretion, we analyzed the pancreatic cancer single-cell RNA sequencing dataset GSE155698." (PMID 41040532, 2025). "Comparison of TFF2 gene expression in normal pancreas and pancreatic tumor samples revealed a 2.9-fold increase in tumors compared to that of normal pancreatic tissues." (PMID 30533259, 2018). "In order to validate the cellular origin of TFF2, we performed RT–PCR of the selected genes with human pancreatic cancer cell lines." (PMID 30533259, 2018). "The data filtering resulted in a final list of two genes that had little information on pancreatic cancer and immunosuppression: trefoil factor 2 (TFF2) and neuromedin U (NMU)." (PMID 30533259, 2018). "Moreover, our study identified a novel biomarker TFF2 that utilizes readily accessible blood samples to distinguish pancreatic cancer from periampullary adenocarcinoma." (PMID 41040532, 2025). "Further studies are necessary to investigate the biological role of TFF2 in pancreatic cancers." (PMID 30533259, 2018). "We found that TFF2 are expressed in pancreatic cancer cell lines via RT–PCR as well as ELISA." (PMID 30533259, 2018). "Further studies are necessary to confirm the precise role of TFF2 in pancreatic cancer." (PMID 30533259, 2018). "In conclusion, we identified 106 highly upregulated genes for secreted proteins from a public database of pancreatic cancers and provide evidence that TFF2 modulates the function of human dendritic cells by acting as a chemokine for immature DCs and impairing their antigen uptake activity." (PMID 30533259, 2018). "Moreover, TFF2 plays an inhibitory role in breast and pancreatic cancer." (PMID 37193028, 2023). "Our data suggest that TFF2 from pancreatic cancer cells may attract immature DCs and affect the initial stage of DC maturation, thereby contributing to the induction of immune tolerance against pancreatic cancer." (PMID 30533259, 2018). "The data filtering narrowed the number of genes to a final list of four that had limited information on pancreatic cancer as well as immunosuppression: secreted phosphoprotein 1 (SPP1, osteopontin), granulin, trefoil factor 2 (TFF2), and neuromedin U (NMU)." (PMID 30533259, 2018). "TFF2 was found to be significantly overexpressed in pancreatic cancer but not in CCA or HCC, suggesting its higher specificity for PC." (PMID 41040532, 2025). "Notably, TFF2 was significantly upregulated only in pancreatic cancer, whereas it was either downregulated or exhibited no significant changes in other gastrointestinal cancers." (PMID 41040532, 2025).